MYC (MYC proto-oncogene, bHLH transcription factor)
Diseases named in the same sentence as MYC in open-access papers (continued):
Sharing a sentence is not in itself a finding about the gene and the disease.
tumor (continued). "Research has further revealed that MYC-dependent tumor progression requires IL-23 signaling to NK cells, thereby promoting the exclusion of NK cells from the TME." (PMID 40732268, 2025). "Transcriptional dysregulation of the MYC oncogene is one of the most frequent events in aggressive human cancers, but it is also integral to the regulation of the tumor immune microenvironment." (PMID 40299510, 2025). "In these clusters, gene sets related to cell proliferation and tumor initiation were enriched, including pathways such as E2F targets, G2M checkpoint, MYC targets v2, Wnt, PI3K/AKT/mTOR, Notch, TGF-β, and Hedgehog signaling." (PMID 39872221, 2025). "In cancer, MYC is often deregulated and overexpressed, acting as a master regulator of metabolic reprogramming that sustains tumor survival and proliferation." (PMID 40126351, 2025). "A cell line (COLO 320HSR) derived from the same patient tumour provides an interesting comparison in that it harbours linear amplifications of a region of chromosome 8 containing c-MYC on another chromosome." (PMID 40744497, 2025). "Our analysis indicates that SNAPC2 activates several key oncogenic pathways, including MYC, E2F, Notch, and PI3K signaling pathways, all of which are closely associated with tumor proliferation, metabolic reprogramming, and malignant transformation." (PMID 40465781, 2025). "It is possible that p.Ser97Asn is augmenting an already active enzyme in the context of these tumours, possibly to stabilise MYC." (PMID 41152984, 2025). "Our identification of an MYC-driven DNA repair gene signature in SCCOHT cell lines led us to interrogate our findings in tumor samples." (PMID 40647552, 2025). "The indole metabolite I3A can enhance tumor immunogenicity by targeting c‐MYC and AhR degradation, and exert T cell‐dependent antitumor effect in vivo." (PMID 40583248, 2025). "We extended our analysis into the c-MYC and PD-L1 expression downregulation by comparing the expression of the c-MYC and PD-L1 in the lungs of the vector + nanocage-treated tumor-bearing mice and the dose-dependent treatment groups." (PMID 40949131, 2025). "MYC activates the miR-17-92 cluster to promote survival and self-renewal while repressing tumor-suppressor let-7 family members by binding upstream of the let-7a-1/let-7f-1/let-7d cluster." (PMID 41154621, 2025). "The MYC proto-oncogene encodes a DNA-binding factor that governs the transcriptional regulation of genetic information, and MYC protein is essential for DNA replication, with its dysregulation through abnormal activation contributing to tumor development." (PMID 40781291, 2025). "Meanwhile, knockdown of ASNS reduces MYC expression and tumor growth, implicating ASNS as a possible focus for cancer treatment." (PMID 40416363, 2025). "These pathways are frequently upregulated in response to oncogenic drivers such as HPV E6 and E7, which enhance nucleotide synthesis by activating MYC and disrupting tumor suppressor functions." (PMID 40599331, 2025). "To further test the robustness of our protocol, we decided to apply the complete pipeline to a different tumour model, specifically MYC-induced liver tumours." (PMID 39880930, 2025). "Further investigation found that I3A induced tumor immunogenicity depending on down‐regulation of c‐MYC and AhR, two key transcription factors involved in cancer metabolism, leading to increased expression of MHC‐I and antigen presentation machinery molecules." (PMID 40583248, 2025). "Another intriguing aspect of our findings is the connection between dual MYC/complex I disruption and tumor immune modulation." (PMID 40668928, 2025).
tumor (continued). "Oncogenic regulators like E2F1 and MYC drive metastatic tumor environments and intertwine with immunoregulatory pathways, impairing T cell function and reducing immunotherapy effectiveness." (PMID 40299510, 2025). "Tumour cells expressing elevated MYC levels exist in a state of chronic replication stress, characterized by persistent activation of DNA damage checkpoints and elevated mutation rates." (PMID 41561634, 2025). "In conclusion, this pan-cancer analysis identifies p62/SQSTM1 as a conserved, clinically relevant regulator linking oncogenic metabolism (oxidative phosphorylation, ROS, mTORC1, UPR/MYC, and DNA-repair programs) to the tumor immune microenvironment." (PMID 41291343, 2025). "Studies have demonstrated that METTL3 enhances tumor cell proliferation and invasion through the MYC, inhibitor of nuclear factor kappa-B kinase subunit beta (IKBKB), and RELA proto-oncogene, NF-kB subunit (RELA) signaling pathways." (PMID 40678060, 2025). "A recent study demonstrated that, spliceosome-targeted therapies (STTs) induced tumor cell death, particularly in MYC-driven immune-cold TNBC." (PMID 39885614, 2025). "Autologous PBMCs were co-cultured with irradiated tumor cells pre-treated with MYC inhibitors (I-BET726, JQ1) and a STING antagonist (C170) to enhance immunogenicity and train tumor-specific PBMCs." (PMID 40552293, 2025). "We also discover a DNA repair gene signature that is overexpressed in SCCOHT tumor samples compared to normal ovary tissue, pointing to MYC as a key regulator of DNA repair gene expression in these cancers." (PMID 40647552, 2025). "Targeting endothelial MYC using nanoparticles bearing siRNA or miRNA is an efficient strategy for tumor anti-angiogenic therapy to enhance the efficacy of chemo- and immune checkpoint inhibitor-based immuno-therapies." (PMID 40303332, 2025). "MYC regulates fundamental cellular activities involved in intrinsic tumor cell pathways, including growth, differentiation, and metabolism." (PMID 40227591, 2025). "The results show that the TME-responsive nanocomposite hydrogel possesses enhanced anti-tumor efficacy in MYC-amplified OS, which supports further development of rational combination therapy for MYC-amplified tumor treatment." (PMID 39897587, 2025). "FBXW7 is a tumor suppressor that targets several oncoproteins, including MYC and cyclin E, for degradation." (PMID 40072110, 2025). "There is also increasing evidence that oncogenes and/or tumour suppressor genes can reprogramme tumour cell metabolism, including through direct regulation of the proline–glutamine regulatory axis by MYC and p532–4." (PMID 39843491, 2025). "Analysis of the surgical specimens showed that the MYC gene is overexpressed in the PC samples, although at low levels compared to the control group, suggesting a compensatory or regulatory role in the tumor environment." (PMID 41296417, 2025). "ARV-825, a BRD4 PROTAC, exhibits significant antitumor activity in various models (neuroblastoma, thyroid cancer, and T-ALL) by degrading the BRD4 protein and suppressing MYC expression, thereby inhibiting tumor cell proliferation." (PMID 40507967, 2025). "Alternatively, indirect targeting on MYC has been extensively explored to achieve desired anti-tumor effects." (PMID 40290126, 2025). "The bridging interactor 1 (BIN1) protein is a nucleocytoplasmic adaptor protein with tumor-suppressive features, and its interaction with c-MYC can modulate c-MYC-mediated transformation and transactivation." (PMID 40406608, 2025). "NSUN2, functioning as a writer for m5C, emerges as a direct target of MYC, a renowned modulator of tumour cell proliferation, initially identified for its upregulation in malignant skin tumours." (PMID 40008496, 2025). "MYC is one of the most common dysregulated oncogenes in human cancers, which coordinates extensive transcriptional changes and plays a central role in tumor development and maintenance." (PMID 40229260, 2025).
tumor (continued). "Together, MYC and RTKs foster the formation of new blood vessels that supply nutrients and oxygen to the tumor." (PMID 40076599, 2025). "MYC is involved in the recruitment of various cytokines from the tumor microenvironment to promote the transition to a more aggressive and metastatic tumor phenotype." (PMID 40290126, 2025). "SCISSOR+ tumor cells showed higher expression of MYC and EMT characteristics, consisting with the features we used to describe MP pattern." (PMID 39899538, 2025). "FISH analysis of a DLBCL tumor identified an atypical MYC rearrangement in 84% of nuclei, showing atypical patterns (1R2G1F)." (PMID 41010038, 2025). "BRD4 is most enriched in super-enhancers that promote the expression of tumor growth and development-enhancing factors, including c-MYC." (PMID 40650308, 2025). "The proliferating subgroup of tumor cells showed enrichment in the cell cycle- and cell metabolism-related signaling pathways, including E2F/MYC targets, G2/M checkpoint, DNA repair and fatty acid metabolism." (PMID 40670350, 2025). "The methylation of MYC K412 leads to inhibition of CHIP‐mediated MYC degradation, enhancement of MYC protein stability and eventual facilitation of tumor growth." (PMID 40091385, 2025). "Given the metabolic alterations exhibited by KRASG12V/MYC expressing tumor cells, we aimed to exploit these metabolic differences as an entry point for selective targeting of cancer cells." (PMID 40550880, 2025). "MYC also negatively regulates anti-tumor immunity by favoring macrophage influx and decreasing the intratumor infiltration of CD3+ T cells, B220+ B cells, and NKp46+ natural killer (NK) cells." (PMID 39706891, 2025). "Our findings demonstrated that circPVT1 promotes tumor progression through dual mechanisms: cP104aa increases c‐MYC expression by forming a complex with HNRNPK, while circPVT1 enhances c‐MYC expression by binding to the EIF4A3 protein." (PMID 40966379, 2025). "SUMOylation of SETD8, which we have demonstrated to be modulated by PIAS1 and SENP6, stabilizes SETD8 and further enhances its binding with MYC via SUMO‐SIM interaction, leading to increased MYC methylation and tumor progression." (PMID 40091385, 2025). "c-MYC is a widely studied oncoprotein that promotes tumor proliferation and migration by regulating the expression of numerous downstream target genes." (PMID 40675969, 2025). "Compared to WT controls, key proliferation-related pathways, including the G2/M checkpoint, E2F targets, and MYC targets, were significantly downregulated in Zbp1−/− tumor cells, indicating impaired cell cycle progression and proliferative capacity." (PMID 41430036, 2025). "MYCi that interfere with the MYC/MAX complex reduces tumor growth and synergizes with immunotherapies and has well tolerable side effects." (PMID 40488968, 2025). "JPH203, a specific LAT1 inhibitor, can play a role as a novel anti-tumor agent and can be evaluated as an MYC-selective cancer therapeutic in future clinical trials." (PMID 41008653, 2025). "The target gene of miR‐7‐1‐3p, POLR3G, is regulated by the transcription factor MYC and is highly expressed in embryonic stem cells and some tumor cells." (PMID 39964093, 2025). "These tumor cell‐intrinsic events caused by squamocin provoked ER stress and the UPR, leading to ERAD‐mediated degradation of EZH2 and MYC, as well as apoptosis." (PMID 39823459, 2025). "The team also uncovered the overactivation of NOTCH and MYC signaling pathways in tumor LP-like cells compared to their normal counterparts." (PMID 39720912, 2025). "For instance, the amplification of the chromosomal fragment 8q24.2 is associated with amplifications of MYC and NDRG1 located on this fragment and is significantly correlated with homologous recombination deficiency (HRD) across tumour types." (PMID 40332138, 2025).
tumor (continued). "Her laboratory integrated data from unbiased genetic screening and metabolomic profiling to identify multiple cancer-selective metabolic vulnerabilities in MYC-driven MB tumor cells, which are amenable to therapeutic targeting." (PMID 41221269, 2025). "It was found that HIF1α, STAT3, and MYC were highly expressed in tumor tissues and were positively correlated with Linc01559 expression (Figure A2a)." (PMID 40722682, 2025). "It induces core stemness regulators (DCAMKL-1, LGR5, CD133, AFP, CK19, Lin28, c-MYC), establishing chemoresistant tumor-initiating phenotypes." (PMID 41438763, 2025). "The performance of MYC biology supports bioenergetic and biosynthetic activities, particularly in abnormal metabolism, throughout the entire process of tumor development." (PMID 40186663, 2025). "Increasing evidence implies that c-MYC is essential in modulating the tumor's surrounding environment and is engaged in the stromal cell proliferation of and tumor neovascularization." (PMID 40711670, 2025). "The tumor‐promoting effects of circPVT1 were shown to be mediated through the upregulation of c‐MYC via dual mechanisms." (PMID 40966379, 2025). "Elevated levels of hTERT and MYC transcripts contribute to the activation of telomerase, which in turn plays a critical role in sustaining telomere length and promoting tumor cell immortality." (PMID 40076599, 2025). "The differentiated tumour cell compartment within the MYC subclone (C1-diff) was in closer proximity to the proliferating cell compartment within the same subclone (C1-prolif)." (PMID 40335697, 2025). "Therapeutic approaches targeting MYC, including miRNA mimics or small molecules, have shown promise in reducing tumor invasiveness and metastasis." (PMID 40817807, 2025). "The deregulated MYC expression results in uncontrolled cell-cycle progression and accounts for the tumor's impressive growth kinetics." (PMID 41287657, 2025). "MAPK9 has been shown to promote tumor growth by stabilizing MYC and facilitating proliferative signaling—key features of the CMS2 subtype." (PMID 41515982, 2025). "Conversely, the oe-NCL + oe-MYC + oe-NC group demonstrated slower tumor growth, smaller tumor volumes, and a lower ki67-positive cell ratio compared to the oe-NCL + oe-NC + oe-NC group." (PMID 40346484, 2025). "Taken together, these findings suggest that MYC targeting can substantially enhance T cell-mediated tumor cell destruction." (PMID 40732268, 2025). "In tumor cells, continuous stimulation of the JAK2/STAT3 signaling pathway promotes MYC expression and enhances the effects of MYC on cell proliferation and metabolism, promoting the proliferation, survival, and invasion of tumor cells." (PMID 40944417, 2025). "From a translational standpoint, our work demonstrated that metformin can synergize with MYC inhibitors to achieve significantly improved tumor control in vivo." (PMID 40668928, 2025). "MYC directly activates the transcription of miR-17-92, which in turn sustains MYC signaling by repressing tumor suppressors and even MYC itself, forming a feedback loop that supports cancer cell survival and growth." (PMID 40940795, 2025). "Pathway analysis unveiled increased proliferation activities in MVI compared to tumor regions, characterized by upregulation of MYC, E2F, spliceosome, and mitotic recombination pathways." (PMID 39670859, 2025). "We propose a model in which MYC plays a critical role in managing the stress it induces, thereby maintaining a balance that promotes tumor growth." (PMID 40488968, 2025). "c-MYC also activates the L-type amino acid transporter-1 (LAT-1) to promote amino acid transport across tumor cell membranes." (PMID 40299656, 2025). "MYC amplification occurs frequently (17 %) in pancreatic acinar cell carcinomas, which are unique and aggressive tumours." (PMID 39434498, 2025). "Taken together, MYC in tumor cells appears to reduce the number of NK cells in the TME through a number of mechanisms." (PMID 40732268, 2025).
tumor (continued). "Genes downregulated by both agents included those corresponding to stem cell signatures, SMARCA4 target genes, EMT, and MYC targets, tumor invasiveness and TGFB1 signatures." (PMID 41279405, 2025). "Specifically, SETD8 methylates MYC at lysine 412 (K412), disrupting the interaction between MYC and the E3 ubiquitin ligase CHIP, which results in MYC stabilization and ultimately promotes tumor growth both in vitro and in vivo." (PMID 40091385, 2025). "To investigate how concurrent MYC and mitochondrial inhibition shapes tumor metabolism, we performed untargeted metabolomic profiling of MycCaP tumors harvested after 7 days of treatment with vehicle, MYCi975, metformin, or their combination." (PMID 40668928, 2025). "Prospective animal studies or organoid models—feasible with existing xenograft platforms—would provide critical validation of the therapeutic potential of miR‐32‐5p inhibition and its impact on c‐MYC‐driven tumor biology." (PMID 40711670, 2025). "We discuss how MYC balances these stressors to promote tumor growth while evading immune detection and propose strategies to target MYC‐dependent stress responses." (PMID 40488968, 2025). "It is noteworthy that the functionally conserved MYC target gene set that we find enriched after tissue damage was originally detected from tumor cells, suggesting that increased ribosomal biogenesis and metabolic flux drive both cancer and tissue repair." (PMID 40180576, 2025). "Silencing FTH1 leads to increased tumor growth, migration, and chemoresistance, along with upregulation of oncogenes like c-MYC and G9a." (PMID 41378310, 2025). "Since its discovery, it has become clear that understanding the oncogenic function of MYC would be crucial for tumor therapy." (PMID 40488968, 2025). "This aligns with the established role of MYC in tumor immune evasion through Treg activation, though its function in thrombosis appears distinct." (PMID 41210882, 2025). "In contrast, MYC, STAT3, CDH1, and CCND1 were significantly downregulated in tumor tissues compared to normal controls, suggesting a loss of tumor-suppressive or differentiation-related functions." (PMID 40766612, 2025). "MYC is a potential therapeutic target for cancer since it controls both the immune system's responses and the intrinsic development of tumor cells." (PMID 40290126, 2025). "MYC is a widespread transcription factor, and transcriptional dysregulation of MYC is frequently found in tumor cells, leading to tumorigenesis." (PMID 40599234, 2025). "To prove the MYC-mRNA drug safety in the tumor-bearing mice compared to healthy controls, we collected blood on day 25 to assay the blood cells, electrolytes, liver enzymes, kidney function, and pancreatic and biliary function analysis from the 3× IC50 group." (PMID 40949131, 2025). "The tumor suppressive function of PGC1α in PCa is coordinated by transcriptional programs that are driven by ERRα and MYC." (PMID 40268923, 2025). "JQ1, a prototypical BET inhibitor, was the first-in-class compound developed to disrupt BRD4-chromatin interactions, leading to MYC downregulation and tumor growth inhibition." (PMID 41335282, 2025). "At low concentrations (1–10 μM), SPD promoted DHPS-mediated eIF5A hypusination, MYC translation, and tumor cell proliferation." (PMID 41408852, 2025). "In summary, our data elucidate the role of squamocin in the degradation of both EZH2 and MYC across multiple tumor models." (PMID 39823459, 2025). "Exosomes collected from MSCs that had been transfected with either miR‐34a‐5p mimic or Si‐c‐MYC significantly reduced tumor growth and metastasis both in vitro and in vivo." (PMID 40007074, 2025). "Consistent with this clinic landscape, FAK inhibition via knockdown or chemical inhibitors suppressed tumor cell growth largely in the subset of CRC cell lines with low MYC expression." (PMID 40959971, 2025).